ENSG00000278039
Gene: Miscellaneous RNA gene on chromosome X (73,850,487 to 73,850,571, forward strand). Ensembl gene ENSG00000278039.
Gene Ontology:
Biological process: dosage compensation by inactivation of X chromosome